GC (GC vitamin D binding protein)
Description:
Involved in vitamin D transport and storage, scavenging of extracellular G-actin, enhancement of the chemotactic activity of C5 alpha for neutrophils in inflammation and macrophage activation.
Synonyms: DBP; VDB; Gc-MAF; GcMAF; DBP-maf; VDBP; hDBP; DBP/GC; GRD3; HEL-S-51; VDBG
Tractability: Small molecule: a structure with a bound ligand is known; it has a high-quality binding pocket; it belongs to a druggable protein family. Antibody: UniProt places it where antibodies can reach, with high confidence; its Gene Ontology location is reachable by antibodies, with high confidence; UniProt predicts a signal peptide or a membrane-spanning region. PROTAC: its protein half-life has been measured; a small molecule that binds it is known.
Target class: Secreted protein
Gene: Protein-coding gene on chromosome 4 (71,735,436 to 71,805,527, reverse strand). Ensembl gene ENSG00000145321.
Subcellular location: Secreted
Pathways (Reactome):
Metabolism: Vitamin D (calciferol) metabolism
Gene Ontology:
Molecular function: actin binding; calcidiol binding; molecular carrier activity; vitamin D binding; vitamin transmembrane transporter activity
Biological process: response to nutrient levels; vitamin D metabolic process; vitamin transport; vitamin transmembrane transport
Cellular component: blood microparticle; extracellular exosome; extracellular region; cytosol; lysosomal lumen; cytoplasm
Genetic constraint (gnomAD): Loss-of-function variants: 19 observed, 18.66 expected, observed/expected ratio (o/e) 1.02, 90% interval 0.71 to 1.49. The upper end of that interval is the gene's LOEUF score, 1.49, which puts it in group 6 of 6, group 1 being the genes least tolerant of losing a copy. Missense variants: 238 observed, 251.39 expected, observed/expected ratio (o/e) 0.95, 90% interval 0.85 to 1.05. Synonymous variants: 109 observed, 97.54 expected, observed/expected ratio (o/e) 1.12, 90% interval 0.96 to 1.31.
Homologues: Orthologues: chimpanzee GC (99% identical), macaque GC (92% identical), pig GC (85% identical), dog GC (82% identical), rabbit GC (80% identical), mouse Gc (78% identical), guinea pig GC (76% identical), rat Gc (74% identical), tropical clawed frog gc (42% identical), zebrafish gc (29% identical). Paralogues in human: ALB (23% identical), AFM (22% identical), AFP (21% identical).
Diseases named in the same sentence as GC in open-access papers:
GC is named in the same sentence as 260 diseases in open-access papers, as found by Europe PMC text mining. Sharing a sentence is not in itself a finding about the gene and the disease. The quoted sentences say what the papers report.
vitamin D deficiency (72 papers, 2012 to 2025). A nutritional condition produced by a deficiency of VITAMIN D in the diet, insufficient production of vitamin D in the skin, inadequate absorption of vitamin D from the diet, or abnormal conversion of vitamin D to its bioactive metabolites. "Our analysis identified ten polymorphisms in the GC gene significantly associated with Vitamin D markers, including Calcifediol (25(OH)D), Calcitriol, Vitamin D-binding protein (VDBP), and odds of Vitamin D deficiency (VDD)." (PMID 39861372, 2025). "Our study reports that common variants in vitamin D pathway genes (CYP27B1 and GC) were associated to vitamin D deficiency in rural and urban children of Bangladesh." (PMID 35256680, 2022). "Vitamin D deficiency (VDD) has been related to vitamin D binding protein (GC) gene polymorphism, demographics and lifestyle factors in different populations." (PMID 33228578, 2020). "Previous studies have indicated that specific VDBP polymorphisms, especially the GC genotype, affect binding affinity to 25(OH)D and may be associated with vitamin D deficiency." (PMID 26294193, 2015). "Genetic factors might be a cause of vitamin D deficiency, and the association of PD with single nucleotide polymorphisms (SNPs) in the VDR and vitamin D binding protein (VDBP/GC) have been investigated in PD, such as a possible cerebrospinal fluid (CSF) biomarker in PD." (PMID 35334877, 2022).
diabetes (38 papers, 2011 to 2025). "On the other hand, genetic studies have linked GC allelic variants of VDBP with serum glucose levels and the development of diabetes." (PMID 32664376, 2020). "The Western blot results showed that the expression of TTR was significantly increased in the diabetes group as compared to the control while GC was significantly downregulated." (PMID 37884923, 2023).
COVID-19 (19 papers, 2021 to 2025). A disease caused by infection with severe acute respiratory syndrome coronavirus 2. "Furthermore, DBP, encoded by the GC gene, is known to have independent immunological and actin-scavenging effects that may affect inflammation in COVID-19." (PMID 36830936, 2023). "Also other inflammatory proteins were more abundant in COVID-19 lungs, including different isoforms of alpha-1-acid glycoprotein as well as vitamin D binding protein (GC), which not only transports vitamin D but also acts as immune system activator." (PMID 36526981, 2022).
Sepsis (19 papers, 2009 to 2025). Sepsis is defined as life-threatening organ dysfunction caused by a dysregulated host response to infection. "The western blot was used to confirm the higher expression of GC in the brain of the sepsis group." (PMID 36600206, 2023). "Given the fact that OT/OTR and GC/GR are involved in the regulation of fluid balance and vascular tone, the goal of this study was to further investigate their role and regulation in the heart of sepsis-induced hypotension." (PMID 32477273, 2020).
asthma (17 papers, 2011 to 2026). "In conclusion, this study has shown that genetic variants in the gene encoding the vitamin D binding protein (GC) contribute to asthma susceptibility in a Han Chinese population." (PMID 21810276, 2011). "Specifically, genetic alterations in two critical loci - the vitamin D receptor (VDR) gene and the group-specific component (GC) gene encoding vitamin D-binding protein (VDBP) - have been identified as potential contributors to increase susceptibility to asthma." (PMID 40936925, 2025). "Moreover, the gene that codes for the vitamin D binding protein (GC) has also been described as a factor in susceptibility to developing asthma." (PMID 36839181, 2023). "Importantly, variants in GC gene, which give rise to the two most common electrophoretic isoforms of the vitamin D binding protein, were associated with asthma susceptibility." (PMID 21810276, 2011). "In this study, we tested whether polymorphisms of genes encoding for vitamin D receptor (VDR), vitamin D 25-hydroxylase (CYP2R1) and vitamin D binding protein (GC) were associated with asthma in the Chinese Han population." (PMID 21810276, 2011).
breast carcinoma (13 papers, 2006 to 2025). "Chromosome 13 open reading frame 42 (C13orf42), lactalbumin alpha (LALBA), G protein-coupled receptor class C group 5 member A (GPRC5A), and GC vitamin D binding protein (GC) have been identified as the most highly expressed genes in breast cancer." (PMID 40608007, 2025).
viral infection (13 papers, 2010 to 2025). "The early expression of gC at 4 h post-infection suggested its involvement in initial viral events, indicating a role for gC during the early stages of viral infection." (PMID 39195802, 2024). "We demonstrate that several G4 motifs in R2 form anti-parallel G4 structures and that the formation of these G4s suppresses gC expression at the transcription level during virus infection." (PMID 36630443, 2023). "During ORF14-G4m-HA virus infection, gC was detected as early as 72 h at a significantly higher level than those in wild-type and revertant viruses." (PMID 36630443, 2023). "We found that the expression of this gene appeared at the late stage of viral infection and the gC protein showed a pronounced cytoplasmic staining in infected cells." (PMID 21110887, 2010). "The gB, gC, and gD proteins are also involved in other viral infection processes." (PMID 37838171, 2023). "In particular, vWF, HRG, PROS1, GC, F2, FGA, and FGB proteins, which are responsible for the expansion of vessels and new vessel formation, modulate blood coagulation and mitigate against vasoconstriction and coagulation caused by virus infection." (PMID 35401544, 2022). "FQ-PCRs were used to detect the expression of the DPV gC gene during viral infection." (PMID 21110887, 2010). "Similar to most viral infection processes, HSV-1 entry into host cells requires viral binding to specific receptors to trigger membrane fusion, and multiple viral entry glycoproteins (gB, gC, gD, gH, and gL) on the surface of the virion play a coordinating role in this process." (PMID 36505792, 2022).
colorectal cancer (10 papers, 2013 to 2024). A primary or metastatic malignant neoplasm that affects the colon or rectum. "Interestingly, we found similar expression patterns of exosomal circLPAR1 in many cancers, including GC, BRCA, BLCA, CESC, KIRC, and LUAD (P > 0.05), and these patterns were all notably different from the pattern in colorectal cancer (P < 0.001)." (PMID 35164758, 2022).
depression (8 papers, 2021 to 2025). "Another study has also shown that depression is inversely correlated with high protein and low fat intake and positively correlated with vitamin D-binding protein (VDBP) concentration when interacting with two polymorphisms (rs7041 and rs4588) in the GC gene, which encodes VDBP." (PMID 38931257, 2024).
mastitis (7 papers, 2017 to 2024). Inflammation of breast tissue during lactation or postpartum due to an obstructed duct or infection. "In 2020 a comprehensive study using a two-step QTL-GWAS approach has been conducted on French dairy cattle breeds that validated a SNP variant (rs436532576) of the GC (vitamin D binding protein) as a probable causative variant for mastitis resistance in Holstein breed." (PMID 36759924, 2023). "Five of the genes considered the most promising candidates (i.e., BoLA-DRB3, CXCL8, GC, NPFFR2, and STAT5A) overlap with mastitis-associated QTL (CM or SCS)." (PMID 36759924, 2023). "This region includes two genes, GC and NPFFR2 that encode the vitamin D-binding protein precursor (88,695,940 to 88,739,180 bp) and the neuropeptide FF receptor 2 (89,052,210 to 89,059,348 bp), respectively, which can be involved in mastitis." (PMID 32264818, 2020). "GC and NPFFR2 gene reported as candidate gene for resistance to mastitis in cattle." (PMID 38437001, 2024). "The NPFFR2 gene (neuropeptide FF receptor 2) along with GC and ADAMTS3 (ADAM metallopeptidase with thrombospondin type 1 motif 3) genes were reported previously to be located within a QTL region affecting clinical mastitis in Norwegian Red dairy cattle." (PMID 31311492, 2019). "The chr6:89.04Mbp locus is adjacent two genes of note: GC and NPFFR2, the former favoured as a candidate gene for milk production and mastitis QTL in other populations, with the latter highlighted by a highly significant missense mutation as a possible causative variant in the current study." (PMID 29246110, 2017).
metabolic syndrome (7 papers, 2013 to 2022). A cluster of metabolic risk factors for CARDIOVASCULAR DISEASES and TYPE 2 DIABETES MELLITUS. "The GC and NADSYN1 genes are associated with the vitamin D status and might contribute to dyslipidemia and overweight independently of 25(OH)D levels." (PMID 24073860, 2013).
migraine (7 papers, 2014 to 2025). "Two single‐nucleotide variants (SNVs) vitamin D receptor (VDR) gene, VDR rs2228570, and VDR rs731236 have shown an association with migraine risk in a previous case–control association study, while an exome sequencing study identified a rare variant in GC vitamin D binding protein gene." (PMID 37553799, 2023). "Using a linkage analysis, exome re-sequencing, and candidate gene re-sequencing, we identified one novel missense variant in GC encoding GC globulin that could play a role in the pathogenesis of melalgia and migraine." (PMID 25147936, 2014). "Thus, the dysfunctional GC globulin affected cytokine release, especially the release of MCP-1, and MCP-1 might play important roles in melalgia and migraine." (PMID 25147936, 2014).
gastric cancer (6 papers, 2010 to 2023). A primary or metastatic malignant neoplasm involving the stomach. "Our results indicated that several EBV genes, LMP-1, BALF1, BALF2, BALF4 and BALF5, may interact with the expression of human GC genes, e.g., the CNTD2 and VANGL2, and the gastric cancer-related pathways, e.g., Jak-STAT signaling and phosphatidylinositol signaling system." (PMID 28415594, 2017).
melanoma (6 papers, 2012 to 2024). A malignant, usually aggressive tumor composed of atypical, neoplastic melanocytes. "Surprisingly, both GL‐1 and GC‐7 could promote Cu2+ accumulation in melanoma cells, and this finding inspires the subsequent study of the regulatory relationship between DHPS and copper metabolism." (PMID 38952061, 2024).
pancreatic cancer (6 papers, 2011 to 2025). "The heterozygote of one GC (vitamin D binding protein) SNP was associated with pancreas cancer risk." (PMID 23826131, 2013). "SNPs in the CYP24A1, CYP2R1, calcium sensing receptor (CASR), vitamin D binding protein (GC), retinoid X receptor-alpha (RXRA) and megalin (LRP2) genes were significantly associated with pancreas cancer risk." (PMID 23826131, 2013). "Critically, GC knockdown profoundly inhibited pancreatic tumor progression." (PMID 40923379, 2025).
cognitive decline (2 papers, 2018 to 2025). "Although the exact cellular mechanisms through which mifepristone reduces Aβ levels and prevents cognitive decline remain to be further investigated, blocking GC actions is an attractive option for possible future therapeutic interventions." (PMID 29491368, 2018).
cutaneous melanoma (2 papers, 2013 to 2020). A primary melanoma arising from atypical melanocytes in the skin. "However, the gene encoding the vitamin D-binding protein (GC) appears in recent studies as a major player in the role of a serum vitamin D level regulator and in Cutaneous Melanoma (CM) predisposition." (PMID 23544077, 2013).
chronic atrophic gastritis (1 paper, 2023). Atrophic gastritis that is persistent and long-standing. "Another advantage offered by digestive endoscopy is the monitoring of gastric lesions other than GC-1 in the context of chronic atrophic gastritis." (PMID 36979851, 2023).
colon cancer (1 paper, 2019). "At the gene level, the interaction P-values of <0.05 were observed for CYP27B1 and GC (vitamin D metabolism) and IL10 (inflammation) for CRC and colon cancer." (PMID 31434255, 2019).
corneal disease (1 paper, 2015). "Monoclonal antibodies directed against HSV glycoproteins gB, gC, gD, and gE showed beneficial effects on the severity of corneal disease in mice in former studies." (PMID 25587898, 2015).
glioma (1 paper, 2018). A benign or malignant brain and spinal cord tumor that arises from glial cells (astrocytes, oligodendrocytes, ependymal cells). "The glycoprotein gC can also be retargeted to the human glioma cells through the ligand human glioma-specific peptide sequence (denoted as MG11)." (PMID 30799657, 2018).
head and neck cancer (1 paper, 2023). A primary or metastatic malignant neoplasm affecting the head and neck. "Another study examined the influence of genetic sequence variants (GSVs) in the vitamin D3 metabolism pathway, candidate-based GSVs, i.e., VDR, GC, CYP24A1, CYP27A1, CYP27B1, and CYP2R1, on overall survival (OS) and second primary cancer (SPC) in head and neck cancer patients." (PMID 37299554, 2023).
Hepatic steatosis (1 paper, 2025). Steatosis is a term used to denote lipid accumulation within hepatocytes. "Our previous work in adolescents with hepatic steatosis also detected EV-derived proteins involved in complement activation and lipid metabolism, several of which exhibit high hepatic expression (e.g., FGL1, RBP4, GC)." (PMID 41354933, 2025).
herpes zoster (1 paper, 2018). A common dermal and neurologic disorder caused by reactivation of the varicella-zoster virus that has remained dormant within dorsal root ganglia, often for decades, after the patient's initial exposure to the virus in the form of varicella (chickenpox). "Expression of VZV gC is sparse in cultured cells but plentiful in human skin during herpes zoster." (PMID 30568636, 2018).
herpetic keratitis (1 paper, 2019). "This could explain why herpetic keratitis is less severe in rabbits infected with a gC-deficient strain of HSV-1 during acute infection." (PMID 31414985, 2019).
hypoglycaemia (1 paper, 2014). "In the nonexercised animals (GC and GR), hypoglycaemia was already present 15 min after insulin injection and its lowest values were recorded at 60 and 120 min." (PMID 24719616, 2014).
ischemic stroke (1 paper, 2021). A stroke disorder caused by obstruction of blood flow to the brain, due to thrombotic (local blood clot formation) or embolic (due to a blood clot or other material traveling from another site) event. "We explored various in vitro and in vivo ischemia/reperfusion models and confirmed that γ-GC reduced ischemic stroke injury by inhibiting apoptosis via the PERK-eIF2α-CHOP and IRE1α-TRAF2-JNK axes." (PMID 34824669, 2021).
lymphoma (1 paper, 2017). A malignant (clonal) proliferation of B- lymphocytes or T- lymphocytes which involves the lymph nodes, bone marrow and/or extranodal sites. "In lymphoma, SIOMICS found four motifs similar to the motifs of SP1, MAZ, GC and the CAC-binding protein, respectively." (PMID 28684851, 2017).
medulloblastoma (1 paper, 2007). A malignant, invasive embryonal neoplasm arising from the cerebellum. "The GC-15 monoclonal antibody, raised against a conserved carboxy-terminal peptide sequence, found in p73β isoforms, also detected comparable levels of TAp73 protein in established cell lines and in primary medulloblastoma samples." (PMID 17626635, 2007).